MARCKS (myristoylated alanine rich protein kinase C substrate)
Diseases named in the same sentence as MARCKS in open-access papers (continued):
Sharing a sentence is not in itself a finding about the gene and the disease.
bladder cancer (3 papers, 2014 to 2025). "The GSEA results also indicated that low expression of the MACC1, GRB10 and MARCKS genes, along with high expression of the NINJ2 gene, were associated with tumourigenesis, including breast, pancreatic and bladder cancers." (PMID 39926275, 2025). "In bladder cancer, MARCKS expression is induced under hypoxia." (PMID 24977165, 2014).
diabetes (3 papers, 2015 to 2023). "Phosphorylation dead MARCKS (PD-MARCKS) reversed maternal diabetes-induced cellular organelle stress, apoptosis and delayed neurogenesis in the neuroepithelium and ameliorated neural tube defects." (PMID 30655546, 2019). "MARCKS-PD diminished the HG-induced or maternal diabetes-induced p-MARCKS signals and restored the colocalization of MARCKS and Tom20." (PMID 30655546, 2019). "The proximity ligation assay confirmed the interaction between MARCKS and Tom20 under the nondiabetic or NG conditions, whereas MARCKS-PD restored the interaction between MARCKS and Tom20 disrupted by maternal diabetes or HG." (PMID 30655546, 2019). "MARCKS-PD prevented the dissociation of MARCKS from the ER induced by HG in vitro and maternal diabetes in vivo." (PMID 30655546, 2019). "Subsequently, we assessed the functionality of maternal diabetes-induced MARCKS phosphorylation using a transgenic (Tg) mouse line with MARCKS-PD overexpression in the developing neuroepithelium." (PMID 30655546, 2019). "MARCKS-PD ablated caspase 3 and caspase 8 cleavage in embryos exposed to diabetes and reduced the number of apoptotic neuroepithelial cells in embryos from diabetic dams compared to that in embryos from nondiabetic dams." (PMID 30655546, 2019). "MARCKS-PD overexpression in the neuroepithelium reversed the maternal diabetes-suppressed calnexin-MARCKS colocalization." (PMID 30655546, 2019). "Further investigation indicated that restoring SIRT2 expression attenuated maternal diabetes-induced NTDs, suggesting that SIRT2-induced MARCKS deacetylation exerts a protective effect on neuroepithelial cells through the inhibition of MARCKS phosphorylation." (PMID 30655546, 2019).
Hypertension (3 papers, 2022 to 2024). The presence of chronic increased pressure in the systemic arterial system. "Excessive sodium retention and hypertension are caused by excessive protein expression and activity of ENaC and presumably its adaptor protein MARCKS and proteases that regulate them." (PMID 36671451, 2022). "It is possible that excessive increases or decreases in MARCKS‐mediated vascular contractility may contribute to vascular diseases associated with profound changes in vascular tone such as hypertension and sepsis." (PMID 39691873, 2024). "Proteases known to cleave both ENaC and MARCKS have been shown to contribute to the development of high blood pressure, or hypertension." (PMID 37569859, 2023). "Therefore, in this study we tested the hypothesis that administering a physiological dose of hAAT to hypertensive diabetic db/db mice will alleviate hypertension by decreasing ENaC and MARCKS protein expression and activity." (PMID 36671451, 2022).
lung diseases (3 papers, 2021 to 2024). "Moreover, MARCKS was proved to be involved in the pathophysiology of various lung diseases." (PMID 35563590, 2022).
lymphoma (3 papers, 2013 to 2021). A malignant (clonal) proliferation of B- lymphocytes or T- lymphocytes which involves the lymph nodes, bone marrow and/or extranodal sites. "Since MARCKS is a known regulator of PI3K signaling, it may have a further role in advancing the EBV-induced effects of increasing cell proliferation, genomic instability, and decreasing cell death in EBV-associated lymphomas." (PMID 33958003, 2021).
non-small cell lung carcinoma (3 papers, 2019 to 2021). A group of at least three distinct histological types of lung cancer, including non-small cell squamous cell carcinoma, adenocarcinoma, and large cell carcinoma. "In fact, recently a biopharmaceutical company developing anti-MARCKS technology demonstrated the highly promising clinical efficacy without any serious adverse events of a novel peptidomimetic BIO-11006 that blocks MARCKS phosphorylation, from a phase 2 study in non-small cell lung cancer." (PMID 33958003, 2021).
ovarian tumor (3 papers, 2016 to 2017). "Thus, MARCKS protein was overexpressed in ovarian tumor stroma as compared to epithelial cells." (PMID 29295532, 2017). "In GSE40595, we performed gene set enrichment analysis (GSEA) in 31 microdissected ovarian tumor stromal samples and identified that the “ECM-RECEPTOR-INTEREACTION” as a significantly enriched signature among the gene sets positively correlated with MARCKS expression (NES=1.69, FDR q=0.019)." (PMID 27081703, 2016).
Senile plaques (3 papers, 2015 to 2022). Senile plaques are extracellular deposits of amyloid in the gray matter of the brain. "In senile plaques in AD, MARCKS coexists with PKC and Aβ, and the phosphorylation of MARCKS is considered to be a marker of PKC activation, which is associated with neuroprotection." (PMID 36307893, 2022). "Aβ, the main component of senile plaques and the putative toxic species underlying AD pathology, causes MARCKS phosphorylation through PKC and MAPK, as well as MARCKS upregulation, when applied exogenously in cultured neurons and microglia." (PMID 26528135, 2015).
Sepsis (3 papers, 2022 to 2024). Sepsis is defined as life-threatening organ dysfunction caused by a dysregulated host response to infection. "The review indicates the possibilities for MARCKS as a therapeutic target for vascular disease involving dysfunctional cell proliferation and migration, endothelial barrier permeability, and vascular contractility such as atherosclerosis, systemic and pulmonary hypertension, and sepsis." (PMID 39691873, 2024). "In contrast, another group reported that MARCKS promotes proinflammatory cytokine expression in macrophages and demonstrated that inhibition of MARCKS using the myristoylated N-terminal sequence (MANS) peptide suppresses pro-inflammatory cytokines and attenuates sepsis in a mouse model." (PMID 37949888, 2023).
amyotrophic lateral sclerosis (2 papers, 2015 to 2021). Amyotrophic lateral sclerosis (ALS) is a neurodegenerative disease characterized by progressive muscular paralysis reflecting degeneration of motor neurons in the primary motor cortex, corticospinal tracts, brainstem and spinal cord. "Likewise, MARCKS etiology and potential as a treatment target should be explored in other neurodegenerative diseases, such as amyotrophic lateral sclerosis (ALS) and Huntington’s disease, where dendritic spine loss has been observed to preclude neurodegeneration." (PMID 26528135, 2015).
dementia (2 papers, 2015 to 2023). Loss of intellectual abilities interfering with an individual's social and occupational functions. "MARCKS is also a marker of neurite degeneration in mouse models of early-stage PD/dementia with Lewy bodies, suggesting transdiagnostic effects across neurodegenerative disorders." (PMID 37328865, 2023). "Furthermore, additional proteins which were consistently altered in both the FLNC-, GRN- and VCP-unique datasets, e.g. GFAP, NPTN, DBI, PRDX6, MARCKS and BSN, are closely associated with cognitive function, dementia and pathological aging." (PMID 26555887, 2015).
depression (2 papers, 2019 to 2021). "As a read-out of peripheral activity of the sympathetic nervous system, it might therefore be worthwhile to study phosphorylation levels of MARCKS in white blood cells of depression patients." (PMID 31362361, 2019). "MARCKS and GAP-43 have been shown to play a role in depression and have been studied in postmortem brains of depressed and suicidal patients." (PMID 33515455, 2021). "High cortisol levels, high α-amylase, PKC-activity, MARCKS-phosphorylation, and high GLUL are tentatively biomarkers for this group of patients with stress-induced depression." (PMID 31362361, 2019). "The evidence that PKC may also be involved in depression is based on the observation that treatment with antidepressants increased phosphorylation of PKC substrates such as GAP-43 and MARCKS." (PMID 33515455, 2021).
Hyperglycemia (2 papers, 2019 to 2025). An increased concentration of glucose in the blood. "MARCKS binds the membranes of mitochondria and the ER, and the phosphorylation of MARCKS caused by hyperglycemia causes it to dissociate from these intracellular membranes in embryos during the neurulation stage." (PMID 30655546, 2019). "Elevated free fatty acids and hyperglycemia augment DAG concentrations, hence activating conventional PKC isoforms that phosphorylate MARCKS (myristoylated alanine-rich C-kinase substrate)." (PMID 41010046, 2025).
Insulin resistance (2 papers, 2015 to 2022). Increased resistance towards insulin, that is, diminished effectiveness of insulin in reducing blood glucose levels. "It has been shown that CA can reduce TC, triglyceride (TG), ALT, AST, and insulin resistance, inhibit the expression of pro-inflammatory factors and adipogenic genes, and improve the expression of myristoylated alanine-rich protein kinase C substrate (MARCKS)." (PMID 36016562, 2022). "This picture of the differential proteome corroborates previous positions about the effects of insulin resistance and raises interesting hypothesis about the implication of other proteins such as PACAP and MARCKS in the onset of insulin resistance in duodenum." (PMID 25950531, 2015).
invasive breast carcinoma (2 papers, 2015 to 2016). A carcinoma that infiltrates the breast parenchyma. "Among the genes identified, myristoylated alanine-rich C-kinase substrate (MARCKS) was found to be highly associated with αSMA expression in EOC tumor stroma, and was notably overexpressed in tumor stroma of both ovarian and invasive breast cancer." (PMID 27081703, 2016). "Interestingly, phospho-MARCKS signals were significantly lower in noninvasive tumors compared to those invasive breast carcinomas and lymph node metastatic tumors (p = 0.048)." (PMID 26015406, 2015).
ischaemic stroke (2 papers, 2025). "Recently, MARCKS has been proposed as a potential biomarker for ischemic stroke and a prognostic marker for endometrial cancer." (PMID 40960646, 2025). "MARCKS has been suggested as a therapeutic target to promote axon regeneration after CNS injury, including in spinal cord and optic nerve regeneration, and as having roles in ischaemic stroke." (PMID 41488750, 2025).
mantle cell lymphoma (2 papers, 2016 to 2021). Mantle cell lymphoma is a rare form of malignant non-Hodgkin lymphoma affecting B lymphocytes in the lymph nodes in a region called the ``mantle zone''. "In patients with mantle cell lymphoma (MCL), specifically, the Ser159/163 phosphorylated form of MARCKS has been reported to be upregulated." (PMID 33958003, 2021).
mood disorder (2 papers, 2013 to 2021). A cognitive disorder a disturbance in which the person's mood is hypothesized to be the main underlying feature. "Alterations in MARCKS expression in mood disorders are also suggested by other studies such as lithium-induced decrease in MARCKS expression in rat hippocampus and increased MARCKS expression in platelets of BP patients." (PMID 33515455, 2021). "One of the substrates for phosphorylation by protein kinase C, myristoylated alanine-rich C kinase substrate (MARCKS), involved in neurotransmitter release and re-uptake, was postulated to play a role in mood disorders." (PMID 25408895, 2013).
osteoarthritis (2 papers, 2021 to 2024). A noninflammatory degenerative joint disease occurring chiefly in older persons, characterized by degeneration of the articular cartilage, hypertrophy of bone at the margins and changes in the synovial membrane. "Firstly, the identified APDEGs—MARCKS, ZFAND5, BCL6, FOSL2, ELL2, and SGCD—may provide deeper insights into osteoarthritis pathogenesis." (PMID 39376659, 2024). "In addition, the comparison between our data and osteoblasts from mice cultured in vitro revealed that several genes (e.g., SLPI, MARCKS, CPE etc.), which are not correlated with osteoarthritis pathogenesis, show fundamental differences of expression levels between human and mouse osteoblasts." (PMID 34428745, 2021).
triple-negative breast carcinoma (2 papers, 2017 to 2022). An invasive breast carcinoma which is negative for expression of estrogen receptor (ER), progesterone receptor (PR), and human epidermal growth factor receptor 2 (HER2). "In a study concerning triple-negative breast cancer (TNBC), the direct role of MARCKS in resistance to PAC has been reported." (PMID 35628654, 2022).
acute myeloid leukemia (1 paper, 2022). Acute myeloid leukemia (AML) is a group of neoplasms arising from precursor cells committed to the myeloid cell-line differentiation. "It is worth to mention that a few genes with a role in acute myeloid leukemia: GRB2, CSFIR, MARCKS and PDGFB were upregulated; FLT1, IL6, PIK3C2B, BALAP3 and MAPK10 were downregulated." (PMID 36413544, 2022).
adenoma (1 paper, 2024). A neoplasm arising from the epithelium. "Given our observation that CDX2++ cells most directly reflect the progression from adenoma to cancer, we evaluated the relative abundance of candidate proteins MARCKS, CD99, and DMBT1." (PMID 39252972, 2024). "To determine if protein patterns specific to CDX2- stromal and CDX2++ epithelial cells could be replicated using alternative methods, we orthogonally investigated DMBT1, CD99, and MARCKS as potential markers for adenoma stratification." (PMID 39252972, 2024). "Specifically focusing on CDX2++ epithelial cells within high dysplasia regions, we suggest MARCKS, CD99, and DMBT1 as potential indicators for the transition from adenoma to carcinoma." (PMID 39252972, 2024).
autistic disorder (1 paper, 2025). "Data from the Jensen Lab indicate that the MARCKS gene is associated with autistic disorder." (PMID 40565366, 2025).
brain malformations (1 paper, 2017). "Although these results suggested that either HDAC2 or MARCKS alone might not cause brain malformations, haploinsufficiency of both genes may be relevant to MICPCH due to the collapse of the interaction between them." (PMID 28783747, 2017).
Burkholderia Infections (1 paper, 2017). Infections with bacteria of the genus BURKHOLDERIA. "We focused on the role of the novel protein kinase C isoform, PKC-η, in Burkholderia infection and characterized PKC-η/MARCKS signaling as a key event that promotes the survival of unopsonized B. thailandensis CDC2721121 within host cells." (PMID 28638804, 2017).
cardiac hypertrophy (1 paper, 2024). "A useful template might be the recent interesting findings proposing that regulation of N‐myristylation, MARCKS, and PIP2 levels are associated with cardiac hypertrophy and failure." (PMID 39691873, 2024).
Cerebral ischemia (1 paper, 2022). Restriction of arterial blood supply to the brain associated with insufficient oxygenation to support the metabolic requirements of the tissue. "The Ixeris sonchifolia Hance injection can reduce the expression of the ROK-α protein and mRNA, inhibit the phosphorylation of PKC-δ and MARCKS, and play a protective role in cerebral ischemia." (PMID 35265143, 2022). "On the one hand, the ROK-α expression was decreased by downregulating the activities of the Rho A/ROK-α and PKC-δ/MARCKS signal pathways, and the phosphorylation of PKC-δ and MARCKS was decreased by the interaction, thus alleviating cerebral ischemia cell damage." (PMID 35265143, 2022).
cholestasis (1 paper, 2017). Impairment of the bile flow caused by obstruction within the liver, or outside the liver in the bile duct system. "It is concluded that cAMP and TUDC reverse TLC‐induced cholestasis by inhibiting the TLC/PKCε/MARCKS phosphorylation/PM‐MRP2 retrieval pathway." (PMID 29192063, 2017). "Thus, cAMP and TUDC may reverse TLC‐induced cholestasis by inhibiting the TLC/PKCε/MARCKS phosphorylation pathway." (PMID 29192063, 2017). "Based on these results, we conclude that the reversal of TLC‐induced cholestasis by cAMP and TUDC involves, at least in part, inhibition of TLC‐mediated activation of the PKCε/MARCKS phosphorylation pathway." (PMID 29192063, 2017).
choriocarcinoma (1 paper, 2025). An aggressive malignant tumor arising from trophoblastic cells. "Choriocarcinoma is associated with MARCKS, DAB2, ENPEP, and TIMP1." (PMID 40565366, 2025).
choroidal melanoma (1 paper, 2011). Malignant tumor of melanocytes of the choroid. "Additionally, the over expression of MARCKS inhibits proliferation of human tumor-derived choroidal melanoma cells." (PMID 21436996, 2011).
Crohn disease (1 paper, 2025). A gastrointestinal disorder characterized by chronic inflammation involving all layers of the intestinal wall, noncaseating granulomas affecting the intestinal wall and regional lymph nodes, and transmural fibrosis. "One SNP (rs4945943) and MARCKS protein were important features of LD for the prediction of Crohn’s disease." (PMID 40941714, 2025).
dementia with Lewy bodies (1 paper, 2018). "Here, we demonstrate that similar changes in MARCKS occur in Parkinson’s disease (PD) and dementia with Lewy bodies (DLB) pathologies in both mouse models and human patients." (PMID 30225354, 2018).
diabetic nephropathy (1 paper, 2023). "Another limitation is that we did not investigate whether increased MARCKS proteolysis in diabetic db/db kidneys increases the risk of developing diabetic nephropathy." (PMID 37569859, 2023).
E. coli infection (1 paper, 2021). "Expression of engulfment mediators MARCKS, RhoB, and CDC42 were reduced or unchanged following succinate or lactate treatment and increased in itaconate-treated macrophages following E. coli infection." (PMID 34350128, 2021).
hereditary nonpolyposis colorectal cancer (1 paper, 2012). "It has been shown that MARCKS (a gene which encodes myristoylated alanine-rich C-kinase substrate) has high frequency frameshift mutations during carcinogenesis in hereditary nonpolyposis colorectal cancer (HNCC)." (PMID 22417299, 2012).
Infertility (1 paper, 2025). "These proteins with high intrinsic disorder and LLPS propensity, such as myristoylated alanine rich C-kinase substrate (MARCKS; UniProt ID: P29966) and nuclear transition protein 2 (TNP2; UniProt ID: Q05952) could serve as potential targets for understanding acrosome deformities and infertility." (PMID 40407495, 2025).
insulinoma (1 paper, 2016). "TIRF imaging of MIN6 insulinoma cells co-expressing an mCherry-tagged DAG sensor and the PKC activity detector MARCKS-GFP showed that K+-mediated membrane depolarization induced repetitive, brief (<10 s) and pronounced DAG elevations." (PMID 27226533, 2016).
invasive ductal carcinoma (1 paper, 2015). "In our clinical observations, phospho-MARCKS levels were significantly increased in invasive ductal carcinoma and high grade tumors." (PMID 26015406, 2015).
knee osteoarthritis (1 paper, 2024). "Specifically, cinnamaldehyde may affect knee osteoarthritis by regulating apoptosis-related genes such as ZFAND5, BCL6, ELL2, FOSL2, MARCKS, and SGCD." (PMID 39376659, 2024).
Listeria monocytogenes infection (1 paper, 2023). "For example, during Listeria monocytogenes infection, miR-21 was upregulated in mice, and miR-21 then targeted MARCKS and RhoB, which depressed L. monocytogenes intracellular replication." (PMID 37239318, 2023).
lung tumor (1 paper, 2018). "Furthermore, expression levels of the downstream markers of the corresponding microRNAs, namely PTEN, MARCKs, TPM-1, PDCD4, SPRY-2, ETS-1, ZEB-2, FGFRL-1, EFNA-3, and k-RAS were downregulated in the lung tumor lesions of patients with the underlying condition compared to non-COPD patients." (PMID 29371906, 2018). "Levels of markers regulated by histone acetylation such as PTEN, MARCKs, EGFL-7 (almost significant decrease), FGFRL-1, SNAIL-1, P63, and k-RAS were significantly reduced in the lung tumors compared to non-tumors only in patients with LC-COPD." (PMID 29371906, 2018).